INS (insulin)
Diseases named in the same sentence as INS in open-access papers (continued):
Sharing a sentence is not in itself a finding about the gene and the disease.
metabolic syndrome (continued). "The possible explanation for this may be, diets high in fruits and vegetables can protect against dyslipidemia because vitamins, minerals, and other multiple nutritional factors in fruits and vegetables may decrease inflammation and oxidative stress, insulin sensitivity, and blood pressure." (PMID 37355585, 2023). "In addition, luteolin could increase the uptake of FFAs from plasma by adipocytes to activate PPAR-γ, thereby reducing dyslipidemia and improving hepatic insulin sensitivity." (PMID 37036026, 2023). "RCI-1502 may alleviate dyslipidemia by stimulating phosphorylation and adenosin monophosphate kinase activation, exerting direct effects on vascular endothelium, decreasing the inflammatory response, and improving insulin sensitivity and glucose tolerance." (PMID 36860672, 2023). "In the present study, we speculate that the primary pathway through which GS supplementation improves dyslipidemia in hyperglycemic rats is mainly through enhanced hepatic signaling of insulin depicted by the increased transcriptional activity of Irs1 and Irs2 genes." (PMID 37110174, 2023). "Besides compromised action of insulin and other peptide hormones, ineffective glucose uptake contributes to increased levels of blood glucose, resulting in health issues such as type 2 diabetes, metabolic syndrome, retinopathy, and neuropathy." (PMID 35883660, 2022). "Moreover, CCS exposed to cranial radiation develop growth hormone (GH) deficiency, which is associated with elevated fasting insulin, abdominal obesity, and dyslipidemia, independent of radiation dose." (PMID 35743665, 2022). "Furthermore, lack of and alternations in hormone-sensitive lipase expression in different cell types cause high levels of triglycerides, which lead to profound effects on whole-body homeostasis, including alterations in insulin signaling and dysregulation in lipid hydrolysis (dyslipidemia)." (PMID 36530555, 2022). "Indeed, we could not rule out the possibility that some key parameters, such as glucose, insulin, and glucagon, may attenuate the relationship between the ANGPTL4 and SUA-associated dyslipidemia." (PMID 35711366, 2022). "Therefore, atherogenic dyslipidemia induced by insulin resistant may contribute to the development of NAFLD." (PMID 35203610, 2022). "The effect of diet supplementation with GP and GP extract (GPE) on insulin-sensitive tissues (adipose, liver and, muscle) was evaluated with an experimental model of metabolic syndrome (MetS)." (PMID 36290748, 2022). "Therefore, elevated activity of RAAS, increased insulin resistance and chronic systemic inflammation may help to explain the pathogenesis of metabolic syndrome in subjects with SRCs." (PMID 36408037, 2022). "We aimed to examine the level of hippocampal neurogenesis, and assess learning and anxiety and the level of some proteins involving insulin signaling pathways in rats with Metabolic Syndrome (MetS); and to reveal the relationship among them." (PMID 36474571, 2022). "Participants were compared between groups based on Metabolic Syndrome (MetS) and Insulin-Sensitivity Index (ISI-cal) scores." (PMID 36352897, 2022). "One of the primary metabolic defects in the insulin resistant state is an impairment in insulin-stimulated glucose uptake in the skeletal muscle; this defect in the major glucose clearing tissue has profound effects on systemic metabolism that contribute to pathology in the metabolic syndrome." (PMID 36303906, 2022). "As recently well-reviewed by Sbraccia and colleagues, it is important to understand that the insulin resistance associated with metabolic syndrome is not a general decrease in insulin action across the board - i.e., it does not affect all actions of insulin across all insulin sensitive tissues." (PMID 34863942, 2022).
metabolic syndrome (continued). "Metabolic syndrome (MetS) is defined as having at least three out of five cardio-metabolic conditions that include abdominal obesity, hyperglycemia and impaired insulin sensitivity, hypertriglyceridemia, hypercholesterolemia and hypertension." (PMID 35228593, 2022). "Indeed, the improvement in dyslipidemia through B. aegyptiaca treatment may be related to the increased level and sensitivity of insulin." (PMID 35213996, 2022). "Besides HOMA-IR improvement, we expect to find a positive correlation between active acupuncture and reduction of the levels of triglycerides, total cholesterol, LDL-C, LDL/HDL, fasting glucose, fasting insulin, and serum insulin and an overview improvement of the metabolic syndrome development." (PMID 36292446, 2022). "It is worth noting that IR could promote atherosclerosis not only through mechanisms that involve systemic factors, such as dyslipidemia, hypertension, and a proinflammatory state, but also through the effect of perturbed insulin signaling at the level of the intimal cells." (PMID 35399955, 2022). "Dyslipidemia in PCOS may be consistent with an insulin resistant state." (PMID 36071485, 2022). "The study included 586 women with PCOS, which documented the PCOS phenotype, metabolic syndrome (MetS) diagnosis, body composition, insulin sensitivity, sex hormones, lipid profile, liver function, and transient elastography (TE) in the cohort." (PMID 35052811, 2022). "Furthermore, in subjects with metabolic syndrome, early phase insulin secretion was increased independently from insulin sensitivity, suggesting that hyperinsulinemia might be the primary defect contributing to glucose intolerance." (PMID 34360563, 2021). "To test our hypothesis, we measured the parameters related to metabolic syndrome following chronic dietary intervention with S. siliquosum, including the structure and function of heart and liver, plasma biochemistry, glucose and insulin responses and body composition." (PMID 34064139, 2021). "This study also showed that low serum IGFBP2 was associated with elevated fasting glucose, triglycerides, and low-density lipoprotein (LDL)-cholesterol and positively correlated with insulin sensitivity, which could be a possible biomarker for metabolic syndrome." (PMID 33498859, 2021). "Currently, the coexistence of glucose and lipid metabolism disorders, as well as arterial hypertension, which constitute criteria of metabolic syndrome (MetS), are more and more frequently observed, and concern mainly obese and insulin-resistant individuals." (PMID 34539448, 2021). "Equine metabolic syndrome (EMS) was named after human metabolic syndrome (MetS) and has insulin dysregulation as a central and consistent feature." (PMID 34947937, 2021). "At the same time, platelet hyperactivity is found in metabolic syndrome (MetS), a cluster of conditions related to abdominal obesity, reduced insulin sensitivity and cardiovascular abnormalities." (PMID 34680088, 2021). "The intronic miRNAs hsa-miR-33a and hsa-miR-33b located within Srebp2 and Srebp1 genes, respectively, regulate cholesterol metabolism and modulate fatty acid β-oxidation and insulin signaling in the liver, which may be particularly relevant in the setting of metabolic syndrome." (PMID 35052597, 2021). "However, the potential neuroprotective effects of metformin have been mostly attributed to its anti-inflammatory and anti-coagulative properties, the prevention of metabolic syndrome and the reduction of peripheral insulin levels that affect brain clearance of amyloid β-peptide (Aβ)." (PMID 34676236, 2021). "Moreover, there is evidence showing that CNMA could improve NO balance in cell lines and islet insulin release in rats with metabolic syndrome." (PMID 34335851, 2021).
metabolic syndrome (continued). "In addition, mice receiving the CCL4 antibody showed lower serum insulin levels, higher insulin-positive areas and more intact with large pancreatic volume and closely arranged pancreatic β-cells morphology than the IgG-treated metabolic syndrome mice." (PMID 33968046, 2021). "Adiponectin is an adipocyte-derived protein that plays a major role in metabolic disorders such as type 2 diabetes (T2DM), insulin sensitivity, metabolic syndrome (MetS) and coronary heart disease." (PMID 34779349, 2021). "Metabolic syndrome (MetS) is a group of disorders that encompasses hypertension, cellular resistance to insulin, central obesity, dyslipidemia, and pro-thrombotic inflammatory states." (PMID 32983730, 2020). "It was hypothesized that the prognostic ability of low MEEi can result from its association with both metabolic and hemodynamic alterations, i.e., metabolic syndrome components, the degree of insulin resistance, concentric LV geometry, LV diastolic and discrete systolic dysfunction." (PMID 32824903, 2020). "IR is a pathological situation characterized by impairment of insulin-mediated glucose transport to peripheral cells, which is due to the lack of physiological response of peripheral tissues to insulin action and leads to the metabolic and hemodynamic disturbances known as metabolic syndrome." (PMID 32952944, 2020). "Therefore, it is reasonable to consider the contribution of other metabolic pathways including dyslipidemia or altered insulin sensitivity that might be affected by TXNIP deletion." (PMID 32492941, 2020). "Finally, we will conclude whether correcting the pathways which maintain [pH]i within the skeletal muscle could, in turn, be effective to maintain or restore insulin responses during metabolic syndrome." (PMID 32977552, 2020). "Furthermore, there are documented gender differences in insulin sensitivity and plasma lipid changes that occur during adolescence, with adolescent boys possessing a greater likelihood of expressing features of atherogenic dyslipidemia than girls." (PMID 32033078, 2020). "Metabolic syndrome (MetS) is characterized by a cluster of high blood pressure, central obesity, high serum triglyceride levels, low serum high-density lipoprotein (HDL) cholesterol levels, and high fasting blood glucose, with insulin resistance as an underlying condition." (PMID 32486113, 2020). "Meanwhile, increased circulating fatty acids may also inhibit insulin activity of glucose uptake in peripheral tissues and lipolysis, leading to exacerbation of IR and the development of another vicious circle between IR and dyslipidemia." (PMID 32587566, 2020). "Metabolic syndrome (MetS) is considered as an insulin resistant syndrome comprising impaired glucose tolerance, decreased insulin sensitivity, dyslipidemia, central obesity, and hypertension, all of which are well- established risk factors for CVDs." (PMID 32066446, 2020). "In addition, visceral obesity is expected to increase post-operative morbidity, because visceral adipose tissue secretes a number of adipokines and cytokines leading to a proinflammatory, procoagulant, and an insulin-resistant state, collectively known as the metabolic syndrome." (PMID 30979055, 2019). "Although an aspalathin-enriched green rooibos extract has displayed moderate effect in improving liver function in an insulin-resistant state, currently no study has reported on the impact of aspalathin on the metabolic syndrome associated hepatic complications." (PMID 31048842, 2019). "Indeed, we have reported that daily consumption of RWGP by patients with at least one component of metabolic syndrome, along with their regular diet, significantly improved blood pressure, glycaemia, and postprandial insulin levels together with an overall improvement of antioxidant defense." (PMID 31500172, 2019).
metabolic syndrome (continued). "Moreover, the improvement of IR after modulation of gut dysbiosis with antibiotic and probiotic treatments was also demonstrated, as was an increase in insulin sensitivity induced by gut microbiota transplantation from lean human donors to subjects with metabolic syndrome." (PMID 31540048, 2019). "Later, researchers found that not all higher DG and ceramide levels result in IR, indicating that fatty acid composition of the accumulated lipids (lipid species) may be an important factor for high-fat diet-induced low insulin sensitivity and subsequent metabolic syndromes." (PMID 31417429, 2019). "Therefore, chemical or natural compounds that alleviate ER stress may act as potential insulin-sensitizing agents against aging-induced metabolic syndrome." (PMID 31246177, 2019). "Vitamin D may improve insulin activity that prevents metabolic syndrome." (PMID 30093913, 2018). "The reason is that central obesity, as assessed by WC, is highly correlated with insulin sensitivity, cardiovascular disease, and the other metabolic syndrome components, and central obesity could be an early step in the etiological cascade leading to full metabolic syndrome." (PMID 29849623, 2018). "Of interest was the similarity in each group of waist circumferences, HDL-cholesterol (and in men fasting insulin and glucose) as metabolic syndrome (MetS) components, as well as of apoA-I, Lp(a), CRP, fibrinogen, and total testosterone levels." (PMID 30075607, 2018). "Gorging and snacking have a low level of mood score related to the metabolic syndrome that influences mood negatively in a complex way including activation of the food reward, the dopaminergic axis and the choice of food, altered cortisol level and high insulin resistance in a bi-directional way." (PMID 27068173, 2017). "Walnut consumption (48 g/day) for 4 days increased circulating apo AI and total adiponectin levels in obese subjects with the metabolic syndrome, indicating that even short-term walnut consumption benefits the lipid profile and adiponectin levels which may insulin resistance and CVD." (PMID 29165404, 2017). "Importantly, the inverse relationship remains significant after adjustment for several confounders potentially affecting either circulating IGF-1 or fasting glucagon levels, including age, gender, adiposity, insulin sensitivity, dyslipidemia and glucose tolerance status." (PMID 28881681, 2017). "Furthermore, acute and continuous impaired insulin secretion could contribute to metabolic syndrome under SGA therapy." (PMID 28584269, 2017). "Weight gain is not only a frequent cosmetic deterrent to intensification that is known to lead to non-adherence to insulin therapy, but can also correlate with various components of the metabolic syndrome, predicting increased cardiovascular risk in overweight patients with T1DM." (PMID 29029531, 2017). "Thus, it is not known whether elevated GGT activity influences glucose metabolism and/or insulin sensitivity in T2D or metabolic syndrome mice models." (PMID 28660214, 2017). "Thus, adipocyte-reduction in leptin signaling occurring in aged males may account, at least in part, for the altered insulin signaling and dyslipidemia that these animals experience." (PMID 28744221, 2017). "Calcium reduces blood pressure by modulation of smooth muscle reactivity and vitamin D may reduce dyslipidemia and improve blood pressure through maintenance of calcium homeostasis, stimulation of insulin production and release, and regulation of the renin–angiotensin–aldosterone system." (PMID 28228848, 2017). "The majority of T2D cases occur in the context of a metabolic syndrome leading to a chronic excess of energetic substrates and ectopic fat storage, insulin resistance, elevated levels of inflammatory cytokines and, ultimately, a decrease in insulin secretion and the apoptosis of pancreatic β cells." (PMID 29228058, 2017).
metabolic syndrome (continued). "However, the disease associated genetic variants of PNPLA3 are not linked with risk factors such as insulin sensitivity or body mass index (BMI) and do not affect related metabolic syndromes such as dyslipidemia or type 2 diabetes." (PMID 27757845, 2017). "The chemokine member CCL2 was highly expressed in adipose tissue and contributed to the cells becoming insulin resistant while CXCL2 (or MIP-2), encoding macrophage inflammatory protein 2-alpha (MIP2-alpha), was the main marker of inflammatory reaction in metabolic syndrome." (PMID 27551318, 2016). "In addition, the resistance in the hemodynamic properties of insulin may impair the blood flow in peripheral tissues, which indirectly contributes to the development of the atherogenic dysglycemia and dyslipidemia." (PMID 27412111, 2016). "On the other hand, there are studies which report a significant association between thyrotropin and metabolic syndrome, carbohydrate intolerance, elevated total and LDL cholesterol, and elevated triglycerides as well as between low levels of free T4 and increased insulin concentration." (PMID 26761948, 2016). "Resistance to insulin is characteristic of metabolic syndrome (MetS), which is defined as a cluster of the following cardiovascular risk factors: central obesity, impaired glucose tolerance, dyslipidemia, and hypertension." (PMID 27597980, 2016). "Insulin appears to be an early marker of metabolic derailment which could identify stages at which correction of lifestyle might require subtler and thus easier modifications than in complete metabolic syndrome patients." (PMID 26241903, 2015). "Kamide, in a cell culture study, reported that insulin increased the expression of angiotensinogen and angiotensin II, thus it may be possible that cardiovascular events in subjects with metabolic syndrome could be reduced with the use of agents that block RAAS." (PMID 25582547, 2015). "These latter GO terms suggest that insulin-resistance profoundly alter enterocyte metabolic response to stimulus from it immediate environment, which supports the hypothesis of dysfunctional enterocytes leading to postprandial dyslipidemia in insulin-resistant subjects." (PMID 26376914, 2015). "Furthermore, typical markers of metabolic syndrome (body weight, fasting blood glucose, fasting insulin, and HOMA-IR) were similarly altered by changing the tissue essential fatty acid composition, although fasting blood glucose was not completely reversed in fat-1 mice." (PMID 26062993, 2015). "Not surprisingly, there is much interest in testing established anti-hypertensive therapies for their potential insulin-sensitizing functions which may improve the metabolic parameters as additional benefits, providing a dual protection against the key features of metabolic syndrome." (PMID 25714093, 2015). "Indeed, reduction or loss of insulin action in the liver leads to abnormally increased hepatic gluconeogenesis, glucose production, and lipogenesis, as well as decreased insulin clearance, hepatic glucose uptake, and lipolysis, consequently resulting in dyslipidemia." (PMID 26491440, 2015). "Moreover, insulin outperformed glucose and HbA1c in its association with the metabolic syndrome, its criteria and clusters of non-glycemic criteria." (PMID 26241903, 2015). "The abdominal obesity may play the central role in MS which is the situation of exceeding visceral fat deposited in peritoneal cavity, and will initiate inflammation and dyslipidemia, increase the blood pressure and decrease insulin sensitivity accompanied with abnormal blood glucose." (PMID 28510813, 2015). "Hence, compounds that can induce adipogenic differentiation in pre-adipocytes may improve insulin sensitivity and/or act as insulin-mimetics which would potentially improve the management of conditions such as metabolic syndrome." (PMID 25714093, 2015). "Insulin could provide early information in subjects prone to develop metabolic syndrome." (PMID 26241903, 2015).